SNHG28 (small nucleolar RNA host gene 28)
Synonyms: VSIG8-OT1; C1orf204; FLJ39187
Gene: Long non-coding RNA gene on chromosome 1 (159,834,480 to 159,855,071, reverse strand). Ensembl gene ENSG00000188004.
Diseases named in the same sentence as SNHG28 in open-access papers:
SNHG28 is named in the same sentence as 3 diseases in open-access papers, as found by Europe PMC text mining. Sharing a sentence is not in itself a finding about the gene and the disease. The quoted sentences say what the papers report.
leishmaniasis (1 paper, 2024). Infectious disease that is transmitted through the bite of hematophagous female phlebotomine sand flies. "While the role of these upregulated lncRNAs is unclear in leishmaniasis, SNHG28 is recognized as a type of lncRNA, named small nucleolar RNA host gene (SNHG), which is involved in the development and aggressiveness of cancer." (PMID 39639867, 2024).
cancer (2 papers, 2024). A tumor composed of atypical neoplastic, often pleomorphic cells that invade other tissues. "Few of the lncRNAs in the SNHG family are known to be negative regulators of the inflammatory response, while SNHG18, SNHG27, and SNHG28 are reported to be associated with different forms of cancer." (PMID 38426128, 2024).
SNHG28 also shares sentences with these, for which no sentence is quoted: prostate carcinoma (1 paper).